CXXC4 (CXXC finger protein 4)
Description:
Acts as a negative regulator of the Wnt signaling pathway via its interaction with DVL1 (By similarity). Binds preferentially to DNA containing cytidine-phosphate-guanosine (CpG) dinucleotides over CpH (H=A, T, and C), hemimethylated-CpG and hemimethylated-hydroxymethyl-CpG.
Synonyms: IDAX
Target class: Transcription factor
Gene: Protein-coding gene on chromosome 4 (104,468,308 to 104,494,901, reverse strand). Ensembl gene ENSG00000168772.
Subcellular location: Cytoplasm
Subcellular location (Human Protein Atlas): Nucleoplasm; Golgi apparatus
Pathways (Reactome):
Signal Transduction: Negative regulation of TCF-dependent signaling by DVL-interacting proteins
Genetic constraint (gnomAD): Loss-of-function variants: 3 observed, 15.62 expected, observed/expected ratio (o/e) 0.19, 90% interval 0.086 to 0.5. The upper end of that interval is the gene's LOEUF score, 0.5, which puts it in group 2 of 6, group 1 being the genes least tolerant of losing a copy. Missense variants: 307 observed, 396.35 expected, observed/expected ratio (o/e) 0.77, 90% interval 0.7 to 0.85. Synonymous variants: 191 observed, 172.9 expected, observed/expected ratio (o/e) 1.1, 90% interval 0.98 to 1.25.
Homologues: Orthologues: macaque CXXC4 (100% identical), chimpanzee CXXC4 (99% identical), pig CXXC4 (99% identical), mouse Cxxc4 (96% identical), tropical clawed frog cxxc4 (71% identical), dog CXXC4 (71% identical), zebrafish cxxc4 (65% identical). Paralogues in human: CXXC5 (29% identical).
Diseases named in the same sentence as CXXC4 in open-access papers:
CXXC4 is named in the same sentence as 21 diseases in open-access papers, as found by Europe PMC text mining. Sharing a sentence is not in itself a finding about the gene and the disease. The quoted sentences say what the papers report.
gastric cancer (10 papers, 2017 to 2024). A primary or metastatic malignant neoplasm involving the stomach. "This study attempted to investigate the possible function of CXXC4 in gastric cancer and the underlying mechanism." (PMID 32715641, 2020). "We recently found that tumor suppressor CXXC finger protein 4 (CXXC4) was downregulated in gastric cancer and its downregulation was associated with a poor prognosis in gastric cancer patients." (PMID 29262584, 2017). "By doing so, CXXC4 down-regulation was associated with poor outcome in gastric cancer patients." (PMID 29262584, 2017). "GDF15 might be a promising target for clinical treatment of gastric cancer with CXXC4 deficiency." (PMID 29262584, 2017). "In gastric cancer, miR-675-3p (derived from GC-EV) inhibits the expression of the target gene CXXC4 and promotes PD-L1 expression by activating the MAPK pathway, thereby stimulating immune evasion of GC cells." (PMID 38762484, 2024). "CDK18 is expressed at higher levels in gastric cancer cells, where CXXC finger protein 4 (CXXC4) overexpression can assist in the inhibition of immune escape via the CDK18-ERK1/2 axis." (PMID 36769170, 2023). "Gastric cancer (GC) extracellular vesicle (EV) encapsulated miR-675-3p aid in the immune evasion of GC cells by repression of CXXC4 and boosting the expression of PD-L1 via the MAPK signaling pathway." (PMID 36338993, 2022). "Based on the microarray dataset of gastric cancer GSE49051 in the GEO database, we successfully isolated CXXC4 as a significantly down‐regulated gene in gastric cancer, while the StarBase database revealed a significant up‐regulation of ELK1 in gastric cancer." (PMID 32715641, 2020). "CXXC finger protein 4 (CXXC4) has been considered as a novel cancer suppressive factor, including gastric cancer." (PMID 32715641, 2020). "CXXC4 is a CpG‐binding protein which is involved with virus related gastric cancer through regulation of DNA methylation." (PMID 32715641, 2020). "In order to understand the effect of CXXC4 on the proliferative potential and immune escape capability of gastric cancer cells, we overexpressed CXXC4 in SGC7901 cells." (PMID 32715641, 2020). "According to Western blot analysis, compared with adjacent normal tissues, the expression of CXXC4 in gastric cancer declined while the level of p‐ELK1 increased." (PMID 32715641, 2020). "Gastric cancer-derived extracellular vesicles enriched with miR-675-3p inhibit the target gene CXXC4 and elevate PD-L1 expression through the MAPK signaling pathway, thus stimulating the immune escape and cisplatin resistance of gastric cancer cells." (PMID 33230461, 2020). "The results showed that CXXC4 was expressed at a lower level in gastric cancer cell lines compared to the GES‐1 cell line." (PMID 32715641, 2020). "Inhibition of the CXXC4/ELK1/MIR100HG pathway suppressed the immune escape of gastric cancer cells, highlighting a possible therapeutic target for the treatment of gastric cancer." (PMID 32715641, 2020). "Then, RT‐qPCR revealed that the expression of CXXC4 in gastric cancer tissues was notably decreased compared to that of adjacent normal tissues." (PMID 32715641, 2020). "Based on reported studies and bioinformatic analyses, we have been suggested the potential role of CXXC4/ELK1/MIR100HG in gastric cancer." (PMID 32715641, 2020). "Subsequently, differential analysis of the microarray dataset GSE49051 showed that CXXC4 was expressed at a low level in gastric cancer." (PMID 32715641, 2020). "In gastric cancer, CXXC4 abrogated the interaction of ERK1/2 with MEK1/2 via binding to ERK1/2 to inactivate MAPK signaling." (PMID 30042169, 2018). "In gastric cancer, the enhancer of zeste homolog 2 was enriched on CXXC4 promoter region and down-regulated its expression." (PMID 30042169, 2018). "In gastric cancer, the down-regulated CXXC4 contributed to proliferation and anti-apoptosis of cells." (PMID 30042169, 2018).
gastric cancer (continued). "We previously found that CXXC finger protein 4 (CXXC4) was a novel tumor suppressor in gastric cancer." (PMID 29262584, 2017). "In summary, CXXC4 stimulated GDF15 transcription via enhancing Sp1 binding to activate apoptosis in human gastric cancer." (PMID 29262584, 2017). "In the present study, we found CXXC4 activated the transcription of GDF15 to induce apoptosis in gastric cancer." (PMID 29262584, 2017). "To further uncover how CXXC4 affects the apoptosis, we analyzed gene expression profiles before and after CXXC4 depletion or overexpression in human gastric cancer cells." (PMID 29262584, 2017). "Nonetheless, our studies clarified a new signaling pathway of CXXC4/GDF15-induced apoptosis in gastric cancer." (PMID 29262584, 2017). "In summary, the nuclear protein CXXC4 activated apoptosis in gastric cancer through up-regulating its novel potential downstream target GDF15." (PMID 29262584, 2017). "In this report, we demonstrated that CXXC4 inhibited growth of gastric cancer cells as a pro-apoptotic factor." (PMID 29262584, 2017). "As a tumor suppressor, CXXC4 inhibits cell growth by activating apoptosis in gastric cancer." (PMID 36830325, 2023). "Previous studies along with our results confirm that CXXC4 may function as a tumour suppressor in gastric cancer." (PMID 32715641, 2020). "Besides epigenetic regulation, CXXC4 can also promote cellular apoptosis via up‐regulation of growth and differentiation factor 15 in gastric cancer." (PMID 32715641, 2020). "In an attempt to investigate the effects of CXXC4 on the development of gastric cancer, the differential analysis on the gastric cancer microarray dataset GSE49051 was performed; 6924 DEGs were obtained, of which 3449 genes were highly expressed with the remaining 3475 genes being poorly expressed." (PMID 32715641, 2020). "First, we found highly expressed CXXC4 could inhibit the proliferation of gastric cancer cells and enhance the activation of T cells through phosphorylation of ELK1." (PMID 32715641, 2020). "Moreover, in vivo experiments revealed that CXXC4 inhibited immune escape of gastric cancer cells through the ERK1/2 axis." (PMID 32715641, 2020). "Thus, CXXC4 functions as a tumour suppressor in gastric cancer, and can be negatively controlled by enhancer of zeste homolog 2 and participates in mitogen‐activated protein kinase (MAPK) axis to suppress tumour growth." (PMID 32715641, 2020). "Next, we verified the role of the CXXC4/MIR100HG/CDK18‐ERK1/2 axis in gastric cancer." (PMID 32715641, 2020). "We have found previously that CXXC4 served as a tumor suppressor gene in human gastric cancer." (PMID 29262584, 2017). "Therefore, our results opened a new avenue for investigating novel functions of CXXC4 relevant to cancer development and provide important information for the management of human gastric cancer." (PMID 29262584, 2017). "Therefore, we speculated that the regulation of CXXC4 on the proliferation and immune escape potential of gastric cancer cells may be realized by MIR100HG." (PMID 32715641, 2020). "Here, we reported that tumour suppressor protein CXXC4 was able to improve proliferation of CD3+ T cells through ELK1‐mediated regulation of ERK1/2 axis, resulting in an enhanced immune effect to gastric cancer cells." (PMID 32715641, 2020). "Then, the expression of CXXC4 in normal gastric epithelial cell lines, GES‐1, and gastric cancer cell lines SGC7901, BGC‐823, SNU‐1 and HGC‐27 was assessed by Western blot." (PMID 32715641, 2020). "Given the results of our present study, it is likely that CXXC4 was a positive regulator of GDF15 and GDF15 also functioned as a suppressor of tumor progression by inducing cell apoptosis in human gastric cancer." (PMID 29262584, 2017). "More importantly, CXXC4 has been found to inhibit the extent of ETS domain‐containing protein‐1 (ELK1) phosphorylation, which is relevant as phosphorylation of ELK1 promotes the development of gastric cancer." (PMID 32715641, 2020).
gastric cancer (continued). "CXXC4, CXXC finger protein 4; GC, gastric cancer; TNM, tumor, node, metastasis." (PMID 33230461, 2020). "The co‐expression relationship between CXXC4 and ELK1 in gastric cancer was obtained from Chipbase." (PMID 32715641, 2020). "Interestingly, we found CXXC4 and ELK1 were co‐expressed in gastric cancer using the Chipbase website." (PMID 32715641, 2020). "As CXXC4 functioned to be a tumor suppressor and GDF15 was a novel CXXC4 downstream target, we further explored the potential tumor suppressing function of GDF15 in gastric cancer." (PMID 29262584, 2017). "In human gastric cancer, EZH2 promotes the activation of Wnt/β-catenin signaling by down-regulating CXXC4 expression, and several other Wnt pathway antagonists, including NKD1, PRICKLE1, PPP2R2B, AXIN2 and SFRP5, were concordantly silenced by EZH2 in hepatocellular carcinomas." (PMID 27926488, 2017). "We then co‐cultured the transfected gastric cancer cells with CD3+ T cells, followed by flow cytometric analysis, results of which indicated that the number of proliferative CD3+ T cells and the proportion of IFN‐γ+ T cells increased remarkably after overexpression of CXXC4." (PMID 32715641, 2020). "However, the relationship between CXXC4 and ELK1 in gastric cancer is not clear." (PMID 32715641, 2020).
colorectal cancer (4 papers, 2018 to 2023). A primary or metastatic malignant neoplasm that affects the colon or rectum. "In the present study, we found that CXXC4 was down-regulated in the tested colorectal cancer cell lines, which is similar to a recent report." (PMID 30042169, 2018). "Overall, the results presented here suggest that miR-629-5p functions as a tumor promoter by improving proliferation and migration and repressing apoptosis and 5-FU sensitivity in colorectal cancer progression by directly down-regulating CXXC4." (PMID 30042169, 2018). "In this research, we tried to explore the functions of miR-629-5p and CXXC4 in colorectal cancer and to reveal the potential relationship between these molecules." (PMID 30042169, 2018). "The protein level of CXXC4 in the tested colorectal cancer cell lines were all down-regulated, indicating the aberrant expression of CXXC4 in colorectal cancer cell lines." (PMID 30042169, 2018). "MiR-629-5p functions as a tumor promoter by improving proliferation and migration and repressing apoptosis and 5-FU sensitivity in colorectal cancer progression by directly down-regulating CXXC4." (PMID 30042169, 2018). "CXXC4 has been identified as a tumor suppressor and was down-regulated in renal cell, gastric, and colorectal cancers." (PMID 30042169, 2018). "In colorectal cancer, miR-629 was found to be significantly upregulated in colorectal cancer tissues and cell lines, and upregulation of miR-629 enhanced cell proliferation and migration as well as suppressed cell apoptosis by directly downregulating CXXC4." (PMID 33763157, 2021). "A previous study suggested that miR-629 is able to accelerate the progression of cancer by binding to CXXC4 in colorectal cancer cells, which further validates our findings that CXXC4 could be a target gene of miRNA." (PMID 33230461, 2020). "Expressions of CXXC4 in colorectal cancer cell lines were also analyzed by WB assay." (PMID 30042169, 2018). "The TET2-interacting proteins IDAX/CXXC4 and RINF/CXXC5 are overexpressed in a number of solid tumours, including breast cancer and colorectal cancer, and have been reported to negatively affect TET2 stability and function." (PMID 37667220, 2023).
renal cell carcinoma (4 papers, 2018 to 2023). "Conversely, loss of CXXC4 expression has been observed in aggressive renal cell carcinomas, and is associated with reduced survival, which may be due to an increase in cancer stem cells." (PMID 31231651, 2019). "In renal cell carcinoma, lower CXXC4 level was associated with promoted malignant phenotype." (PMID 30042169, 2018). "In renal cell carcinoma, down-regulation of CXXC4 by siRNA resulted in the up-regulation of some cellular proliferation related genes (FGF18, EGR1, and MYCN), the down-regulation of apoptosis inhibitor proteins BIRC7 and XAF1, and some other important tumor progression factors." (PMID 30042169, 2018). "The CXXC4 protein is a negative regulator of Wnt and Ras/MAPK signaling, with the downregulation of CXXC4 promoting malignant phenotype in renal cell carcinoma by activating Wnt signaling." (PMID 36830325, 2023).
hepatocellular carcinoma (3 papers, 2017 to 2020). A malignant tumor that arises from hepatocytes. "Consistent with our findings, previous studies have highlighted that CXXC4 is related to the MAPK signaling pathway in hepatocellular carcinoma, and activation of the MAPK signaling pathway can promote the development of GC." (PMID 33230461, 2020).
colon cancer (2 papers, 2020). "Similarly, altered expression of CXXC4 has been previously implicated in the colon cancer recurrence." (PMID 33230461, 2020).
glioma (2 papers, 2021 to 2022). A benign or malignant brain and spinal cord tumor that arises from glial cells (astrocytes, oligodendrocytes, ependymal cells). "Our data indicated that the Wnt pathway activation related genes such as CCN4, FOSL1, LGR6, MMP7, RAC2, SERPINF1 and TCF7 were upregulated, while Wnt pathway inactivation related gene such as CXXC4 was downregulated in radiotherapy treated glioma patients from TCGA database." (PMID 34852024, 2021).
leukaemia (2 papers, 2020 to 2024). "Suggestive of elevated CXXC4 activity, transcriptome analysis using GSEA showed reduced Wnt/β-catenin signaling in Cxxc4-ITD-expressing leukemia samples relative to WT Cxxc4 BM LK cells (data not shown)." (PMID 33205068, 2020). "Indeed, translation inhibition by cycloheximide to block de novo protein synthesis showed that the CXXC4-ITD was maintained at higher levels than WT CXXC4, providing a plausible explanation for its elevated abundance in the mouse leukemia cells." (PMID 33205068, 2020). "This suggests that some CXXC4-ITD mutations may be somatic, whereas others may be present in the germline and predispose to leukemia." (PMID 33205068, 2020).
head and neck carcinoma (1 paper, 2017). A carcinoma that arises from the head and neck region. "The analysis of the occurrence of gene promoter methylation in head and neck carcinoma cell lines indicated that CXXC4, DACT2, HHIP, ZIC1, and ZIC4 are methylated in these tumors." (PMID 27553089, 2017). "On the other hand, we have observed that DACT2 is frequently methylated in both the cells lines and head and neck carcinomas while CXXC4 is methylated to a lesser extent." (PMID 27553089, 2017).
head and neck squamous cell carcinoma (1 paper, 2017). A squamous cell carcinoma that arises from any of the following anatomic sites: lip and oral cavity, nasal cavity, paranasal sinuses, pharynx, larynx, and salivary glands. "In summary, we report that CXXC4, DACT2, HHIP, ZIC1, and ZIC4 are methylated in head and neck squamous cell carcinomas." (PMID 27553089, 2017).
Impaired glucose tolerance (1 paper, 2018). An abnormal resistance to glucose, i.e., a reduction in the ability to maintain glucose levels in the blood stream within normal limits following oral or intravenous administration of glucose. "They identified hypomethylation of two genes, Musashi RNA-Binding Protein 2 (MSI2) and CXXC-Type Zinc Finger Protein 4 (CXXC4), in individuals with T2D and impaired glucose tolerance, compared to healthy controls." (PMID 30564199, 2018).
ovarian carcinoma (1 paper, 2015). A malignant neoplasm originating from the surface ovarian epithelium. "Thus, our analysis suggests the hypothesis that DVL3 amplifications, coupled with decrease in CXXC4 expression, could drive ovarian cancer progression through enhanced activation of the Wnt signaling pathway." (PMID 25572314, 2015).
schizophrenia (1 paper, 2022). A major psychotic disorder characterized by abnormalities in the perception or expression of reality. "In addition, CXXC4 was identified as the top associated gene in a GWAS meta-analysis of schizophrenia and ASD53." (PMID 35292647, 2022).
severe congenital neutropenia (1 paper, 2020). "show that acquisition of a mutation in Cxxc4 results in increased CXXC4 protein levels, reduced TET2 protein, increased inflammatory signaling, and leukemic progression of a CSF3R/RUNX1 mutant mouse model of severe congenital neutropenia (SCN)." (PMID 33205068, 2020).